IL10 (interleukin 10)
Diseases named in the same sentence as IL10 in open-access papers (continued):
Sharing a sentence is not in itself a finding about the gene and the disease.
lupus (continued). "The mechanism of Th1 cell autoregulation through co-induction of IL-10 and IFN-γ might be a further explanation for the observed strong co-expression of IL-10 and IFN-γ in mice with lupus manifestation." (PMID 33572870, 2021). "ZBTB33 binds to a motif in the Ctse locus in a methylation-dependent manner, and subsequently represses the expression of Cathepsin E and IL-10 in murine thymoma EL-4 cells, and in CD4+ T cells of MRL/lpr mice or patients with systemic lupus erythematosus (SLE)." (PMID 34349770, 2021). "At first sight, the observation that in vivo α-IL-10R treatment slightly triggered lupus progression without increasing IL-10 and IFN-γ expression in T cells was paradoxical." (PMID 33572870, 2021). "However, a subset of B cells known as Bregs play a suppressive role, mainly through the actions of IL-10 and TGF-β and have recently emerged as a focus within lupus." (PMID 32655565, 2020). "Overall, the findings in this study revealed the novel effect of IL-33 in suppressing lupus onset in young NZB/W F1 mice, presumably through the protective anti-dsDNA IgM antibodies, IL-10-expressing Breg cells, and upregulation of alternatively-activated M2 macrophage-genes." (PMID 33182616, 2020). "In systemic lupus erythematosus, it was reported that TNF-α could be protective, since its levels and TNF-α/IL-10 ratio were lower in patients with active disease." (PMID 31906962, 2020). "This cell control given at the pre-disease stage did not change the disease severity at 15 weeks of age, suggesting that early introduction of activated IL-10 producing Breg cells, rather than Treg cells, were responsible for the attenuation of lupus." (PMID 33240280, 2020). "PCG may alleviate nephritis in lupus-prone mice by rebalancing the population of splenic CD4+ T cells, particularly by increasing the population of Treg cells secreting both IL-10 and TGF-β1." (PMID 32674502, 2020). "Consistent with this, B cells isolated from lupus-prone mice produce more IL-10 in response to stimulation by CpG oligonucleotides than normal mouse B cells, but not to stimulation through the B-cell receptor or CD40 ligation." (PMID 33240280, 2020). "In a mouse model of systemic lupus erythematosus (SLE), it was found that treatment with pan-HDACi trichostatin A (TSA) led to a decrease in mRNA expression of various inflammatory cytokines such as IL-6, IL-2, IL-10, and IFNγ." (PMID 31067680, 2019). "In in vivo analyses, the simultaneous presence of TGF-β and IL-10 effectively suppressed TLR-mediated antigen-specific immune responses and ameliorated pathologies in imiquimod (TLR7 agonist)-induced lupus model and lupus-prone MRL/lpr mice." (PMID 29963056, 2018). "A combination of hCG and ODN1826 elicited significantly higher levels of IL-10 than individual moieties in lupus-prone mice, an effect not observed in healthy animals." (PMID 30574119, 2018). "Deficiency of IL-10 exacerbates autoimmune pathology in mouse models of systemic lupus erythematosus (SLE), rheumatoid arthritis (RA), and experimental autoimmune encephalomyelitis (EAE), indicating the critical role of IL-10 in the regulation of immune homeostasis." (PMID 29535721, 2018). "Lupus-associated and inflammatory cytokine genes, such as IL4, IL6, IL10 and IL13, are demethylated in lupus T cells and may contribute to disease progression." (PMID 25988383, 2015). "In renal tissue, during active lupus, increasing CD8+FoxP3+ T cells may inhibit T proliferation by cell-cell contact and increase production of suppressive cytokine IL-10." (PMID 24475019, 2014). "When CD24hiCD38hi B cells were removed from the culture, higherfrequencies of CD4+IFNγ+ and CD4+TNFα+ T cellswere noted in healthy individuals but not in systemic lupus erythematosus patients; this effect waspartially IL-10 dependent." (PMID 23566714, 2013). "In the MRL.Fas(lpr) mouse lupus model, B cell-derived IL-10 does not regulate spontaneousautoimmunity." (PMID 23566714, 2013).
lupus (continued). "Blood mononuclear cells were cultured for 24 hours in the presence or absence of PMA,ionomycin, or LPS; significantly more systemic lupus erythematosus CD5+ B cells producedcytoplasmic IL-10 than did controls." (PMID 23566714, 2013). "B cell-specific deletion of IL-10 in MRL.Fas(lpr) mice indicates that B cell-derivedIL-10 is ineffective in suppressing the spontaneous activation of self-reactive B cells and T cellsduring lupus." (PMID 23566714, 2013). "Notably, IL-10 facilitated ABC differentiation in SLE patients as IL-10 restored the generation of T-bet CD11c B cells after RNASE2 silencing Therefore, the RNase2/IL-10 signaling in lupus monocytes promotes ABC formation in SLE." (PMID 39960645, 2025). "Our data revealed amelioration of BTN3A1‐induced lupus‐like changes, such as improved degree of renal injuries and reduced percentage of CD3+, CD8+ T cells, Th1, Th2, Th17 cells, upregulated percentage of Treg cells, and lower expression of IL‐4, IL‐6, IL‐10, IL‐17A, IFN‐γ, TNF‐α, and dsDNA." (PMID 40959207, 2025). "Bregs, in addition to restraining the production of IFN-α from pDCs through IL-10 release, act under normal circumstances to suppress T helper cells and prohibit the production of cytokines such as TNF-α and IFN-γ, an ability that Bregs from lupus patients seem to lack." (PMID 39456692, 2024). "Many studies assess the impact of the IL-10 polymorphism on SLE development but there are no reports on the simultaneous assessment of the gene polymorphism, mRNA expression, and IL-10 concentration among lupus patients." (PMID 38791549, 2024). "The substantial number of Tregs in Dex-NPs treated lupus mice may primarily depend on IL-10 production by DCs since Dex-NPs, but not dexamethasone, induced high IL-10 production in both WT and Fcgr2b-/- DCs." (PMID 37176021, 2023). "Of note, among the multiple serum SLE-associated autoantibody specificities and plasma immune mediators assessed, BLyS levels were increased in lupus relatives and HC who reported chronic fatigue, while IL-10 levels were decreased, irrespective of ACR criteria status (p<0.05)." (PMID 35720322, 2022). "Hence indicating that B cell derived IL-10 can inhibit lupus pathology but has no impact on the overall B cell activation." (PMID 35979356, 2022). "PTPN22 and IL10 gene expression was negatively correlated with Mex-SLEDAI score and were notably downregulated in SLE patients with lupus nephritis." (PMID 36428917, 2022). "In addition, we found the UC-MSCs induced CD1c+DCs in the lupus patients exerted tolerogenic properties by decreasing expression of CD80, CD83, CD86 and HLA-DR, decreasing production of TNFα and keeping production of IL-10." (PMID 31175312, 2019). "Upon repeated injection of apoptotic cells, these mice developed a systemic lupus erythematosus (SLE)-like disease, with increased levels of pro-inflammatory cytokines, such as IL-6, IL-1β, IL-12, autoantibodies, and a decreased level of the anti-inflammatory cytokine, IL-10." (PMID 31665027, 2019). "In the lupus-prone (NZX × NZW)F1 (NZB/NZW) mice model, infiltration of CD3+ T cells and increased mRNA expression of pro-inflammatory mediators such as IL-1β, IL-6, IL-10, interferon (IFN)-γ and transforming growth factor β have been shown in the hippocampi ex vivo." (PMID 25955648, 2015). "Tolerogenic Lactobacillus probiotics reduced Th1/Th17 cell populations, elevated Tregs and IL-10, suppressed pro-inflammatory cytokines (IL-17, IFN-γ) and autoantibodies (ANA, anti-dsDNA, anti-RNP), diminished lipogranuloma mass, and delayed SLE progression in pristane-induced lupus mice." (PMID 40534849, 2025). "The study demonstrates their impact to reduced anti-dsDNA, ANA, and anti-RNP antibodies, alleviated proteinuria and disease severity, boosted CD4+ CD25+ FoxP3+ Tregs, lowered IL-6, and elevated IL-10 and TGF-β, collectively ameliorating SLE symptoms in pristane-induced lupus mice." (PMID 40534849, 2025).
lupus (continued). "Additionally, DNT cells secrete cytokines such as IL-1, IL-8, IL-10, IL-17, TNF-α, and IFN-γ, which can either facilitate immune homeostasis or exacerbate disease activity in conditions such as autoimmune lymphoproliferative syndrome, Sjögren’s syndrome, systemic lupus erythematosus, and psoriasis." (PMID 40443662, 2025). "This case control study used 46 KOA patients (pKOA, n = 30; sKOA, n = 16), and 60 age, gender matched controls (normal healthy, n = 30; systemic lupus erythematosus [SLE] disease controls, n = 30) where serum was assayed for cytokines (TNF-α, IL-1β, IL-6, IL-10) and nitric oxide derivatives (NOx)." (PMID 34543351, 2021). "Unsurprisingly, IL-10 reduced the DNA methylation level of AIM2, lupus B cells showed a lower level of DNA methylation of AIM2, and decreased DNA methylation was found in active SLE B cells." (PMID 34521812, 2021). "Furthermore, when the spleen cells from lupus mice (MRL/lpr mice) were cultured with PD-L1 positive MDSCs, only PD-L1 positive MDSCs form control mice remarkably suppressed plasma cell (CD19-CD138+) population and expanded IL-10 producing B 10 cell (CD19+CD5+CD1d+)." (PMID 33986739, 2021). "In addition, this down-regulation of CD200R1 expression on DCs was also noted in lupus-prone mice along with elevated levels of anti-dsDNA Abs, which could be reversed by CD200-Fc treatment possibly through reducing the productions of IL-6 and IL-10 from DCs." (PMID 31597242, 2019). "Interleukin 10 is considered to be an important regulatory cytokine, yet serum concentrations appear to be paradoxically high in diseases characterised by production of autoantibodies, including AIHA and systemic lupus erythematosus (SLE)." (PMID 27942026, 2016). "Additionally, it was recently shown that selective deletion of IL-10 in B cells did not affect disease parameters in a mouse model of lupus, suggesting that the in vivo effects of endogenous regulation by IL-10-producing B cells may be more subtle than previously thought." (PMID 23940537, 2013). "With respect to sleep, there was no consistent pattern of altered SLE-CSQ scores nor BLyS and IL-10 levels noted in either lupus relatives or HC." (PMID 35720322, 2022).
rheumatoid arthritis (287 papers, 2004 to 2025). A chronic, systemic autoimmune disorder characterized by inflammation in the synovial membranes and articular surfaces. "Chronic autoimmune diseases such as rheumatoid arthritis are associated with increased IL-10 levels." (PMID 41417343, 2025). "The ME/CFS network shows substantial overlap with pathways implicated in multiple sclerosis, rheumatoid arthritis and other chronic inflammatory disorders (shared nodes: IL-2, IL-10, CD4-T cell markers)." (PMID 41057909, 2025). "In Bulgaria, for example, IL-10 polymorphisms have been extensively studied in relation to multiple sclerosis, rheumatoid arthritis, and lupus erythematosus, but to the best of the authors’ knowledge, not in relation to periodontitis." (PMID 39336814, 2024). "In another study on rheumatoid arthritis, exosomes were utilized as carriers to deliver interleukin-10 (IL-10) cytokine-encoding plasmids (IL-10 pDNA) and betamethasone simultaneously." (PMID 37631256, 2023). "Some works showed an association of IL10-1082A/G SNP with autoantibody production in patients with rheumatoid arthritis." (PMID 36233253, 2022). "FcγR crosslinking is also known to induce epigenetic changes, where chromatin remodelling has been described to underlie IC-induced IL-10 secretion in macrophages and contribute to dysregulated inflammatory responses in rheumatoid arthritis." (PMID 35619690, 2022). "While the tested IL-10 variants were linked with altered IL-10 secretion in rheumatoid arthritis, and gastric inflammation, few studies investigated the association between IL-10 genotypes and IL-10 levels in HNC." (PMID 30762321, 2019). "We observed an association of putative IL-10 low producer genotypes with a favourable etanercept response in patients with rheumatoid arthritis." (PMID 26107717, 2015). "A recent small-sample study showed that serum IL-10 was significantly higher in ten rheumatoid arthritis patients carrying the C allele of rs1800872(-592A/C)." (PMID 24040186, 2013). "Polymorphisms in the promotor region of IL-10 are known to influence the risk of rheumatoid arthritis in human beings, by reducing IL-10 transcription and decreasing circulating IL-10." (PMID 21998650, 2011). "Associations with the IL10 −2849 polymorphism or with haplotypes comprising this variant have also been described in other conditions, e.g. in rheumatoid arthritis, decreased female fertility, systemic sclerosis, pre-eclampsia, and in leprosy." (PMID 19412539, 2009). "On the other hand, patients with the rs1800896 (IL10 gene) variant showed a positive response to Etanercept in rheumatoid arthritis, which means the high prevalence of GG genotype in the Qatari population points towards a probable better response to Etanercept as compared to other populations." (PMID 41346622, 2025). "In addition, such higher values for IL-10-producing B cells have already been reported in autoimmune phenomena associated with active rheumatoid arthritis." (PMID 34681587, 2021). "Nonetheless, the novel immunocytokine F8-IL-10 (Dekavil), which use a targeting antibody linked to IL-10 that is now being evaluated in a phase 2 clinical trial in patients with rheumatoid arthritis, may pave the way for its use in IBD patients." (PMID 31052214, 2019). "IL-10 deficiency might promote macrophage polarization toward the proinflammatory M1 phenotype, which contributes to the rheumatoid arthritis inflammation response." (PMID 24742125, 2014). "A polymorphism in IL10 (-1087) has been linked to a number of autoimmune diseases including inflammatory bowel disease, rheumatoid arthritis (RA) and systemic lupus erythematosus." (PMID 20478055, 2010). "For example, in autoimmune conditions like rheumatoid arthritis or multiple sclerosis, the dysregulation of IL-10 production by DC-SIGN+ cells can contribute to disease progression." (PMID 40076949, 2025).
rheumatoid arthritis (continued). "The gut microbiota itself can alleviate inflammatory arthritis, and oral administration of SCFAs has also been demonstrated to ameliorate experimental rheumatoid arthritis in part by the function of increasing IL-10-producing B cells." (PMID 41479667, 2025). "In contrast, anti‐inflammatory properties have been formerly attributed to IL‐4 cytokine on IVD cells and analgesic, chondroprotective activity in combination with IL‐10 in osteoarthritis and rheumatoid arthritis." (PMID 39931581, 2025). "Based on these findings, IL-10 was evaluated as a therapeutic target, and recombinant IL-10 therapy has been attempted in rheumatoid arthritis, Crohn's disease, and HIV infection; however, the results have been unsatisfactory." (PMID 40630332, 2025). "In inflammatory diseases, such as rheumatoid arthritis and ulcerative colitis, MBIs significantly increase the levels of anti-inflammatory cytokine IL-10." (PMID 40281902, 2025). "IL‐4 and IL‐10 are well‐known immunomodulatory cytokines that act as anti‐inflammatory mediators in degenerative joint diseases, including rheumatoid arthritis and osteoarthritis." (PMID 39931581, 2025). "ELISA consistently demonstrates elevated levels of p75NTR, sortilin, TNFα, interleukin-1β (IL-1β), interleukin-6 (IL-6), and interleukin-10 (IL-10) in the serum of patients with rheumatoid arthritis compared to healthy subjects." (PMID 38785946, 2024). "Immunomodulation using IL-10 has been identified as a possible therapeutic in many diseases, including Crohn disease, rheumatoid arthritis, psoriasis, and other immune-mediated syndromes." (PMID 39703903, 2024). "Recombinant human IL-10 has shown efficacy in clinical trials for inflammatory conditions like psoriasis, Crohn’s disease, and rheumatoid arthritis." (PMID 38504987, 2024). "IL10, an anti-inflammatory cytokine, is involved in autoimmune and inflammatory diseases, including lupus erythematosus, myocardial infarction, and rheumatoid arthritis." (PMID 39337647, 2024). "One study analyzing B cell-specific AhR-deficient mice demonstrated that AhR signaling in regulatory B cells (Bregs) induces IL-10 secretion, thereby, dampening inflammatory Th1 and Th17 responses in a murine rheumatoid arthritis model." (PMID 36875083, 2023). "Because TNF-α and IL-1 β production were substantially and long-term inhibited during IL-10 treatment, it was previously tested in the clinical treatment of inflammatory diseases such as rheumatoid arthritis, psoriasis, and inflammatory bowel disease." (PMID 37492521, 2023). "Supplementation with VD3 also results in increased pTreg numbers and IL-10 production in patients with autoimmune and chronic inflammatory diseases, including rheumatoid arthritis, SLE, MS and T1D." (PMID 37175505, 2023). "Consequences of impaired IL-10 function in experimental disease models include chronic inflammatory bowel disease, rheumatoid arthritis, psoriasis, lupus, multiple sclerosis, transplant rejection, cancer, and infection." (PMID 37947634, 2023). "High levels of IL-10 have been documented in systemic lupus erythematosus, multiple sclerosis, rheumatoid arthritis and Sjogren’s syndrome, as well as in autoimmune lymphoproliferative syndrome, acute ulcerative colitis, and Grave’s disease." (PMID 37359549, 2023). "Compared with rheumatoid arthritis patients, in the joint synovium of OA patients, the frequency of IL-10+ B cells was higher, while the total number of IL-10+ cells in synovial B cells was lower." (PMID 37388748, 2023). "On the other hand, CTRP6 enhances IL-10 expression in macrophages and, through inhibition of the alternative pathway of the complement system, can exert anti-inflammatory properties in rheumatoid arthritis patients." (PMID 37047812, 2023).